MIR6865 (microRNA 6865)
Synonyms: hsa-mir-6865
Gene: MicroRNA gene on chromosome 17 (4,970,086 to 4,970,150, reverse strand). Ensembl gene ENSG00000278517.
Homologues: Orthologues: chimpanzee MIR6865 (100% identical).